PDIA6 (protein disulfide isomerase family A member 6)
Diseases named in the same sentence as PDIA6 in open-access papers (continued):
Sharing a sentence is not in itself a finding about the gene and the disease.
Fibroadenoma (2 papers, 2021 to 2023). A benign tumor of the breast characterized by the presence of stromal and epithelial elements. "In women with fibroadenoma, an autoantibody response occurred against VPS35 (p = 0.007 compared to control women), SERBP1 (p < 0.0001 compared to control women), KRT8 (p = 0.03 compared to control women), and PDIA6 (p = 0.003 compared to control women)." (PMID 33976232, 2021).
giant cell tumor (2 papers, 2020 to 2021). A benign, intermediate, or malignant tumor that arises from the bone or soft tissue. "Silencing of PDIA6 significantly decreased the tumor volumes to 42.7% in giant cell tumor stromal cells." (PMID 33761940, 2021). "In addition, miR-127 inhibited tumor growth via targeting cytochrome c oxidase assembly factor 1 homologue (COA1) and protein disulfide isomerase family A, member 6 (PDIA6) in giant cell tumor of bone." (PMID 32051829, 2020).
hepatocellular carcinoma (2 papers, 2018 to 2021). A malignant tumor that arises from hepatocytes. "PDIA6 has also been revealed to be actively expressed in hepatoma cells during Hepatitis C virus replication." (PMID 29404200, 2018).
liver fibrosis (2 papers, 2022 to 2023). "We report a second patient with intrauterine growth retardation, congenital polycystic kidney disease, infancy-onset diabetes, microcephaly, and liver fibrosis caused by a homozygous PDIA6 loss-of-function variant." (PMID 35856135, 2022).
ovarian carcinoma (2 papers, 2017 to 2021). A malignant neoplasm originating from the surface ovarian epithelium. "For PDIA6, among 308 ovarian carcinomas, 147 (47.7%) tissues expressed strong, 148 (48.1%) moderate, and 13 (4.2%) weak positive staining." (PMID 29262583, 2017). "Importantly, overexpression of PDI family members is associated with poor survival in ovarian cancer (p = 0.045 for PDI, p = 0.047 for PDIR, p = 0.037 for ERp57, p = 0.046 for ERp72, p = 0.040 for AGR3) with the exception of PDIA6 (p = 0.381)." (PMID 29262583, 2017). "We observed significant increases in PDI (p = 9.16E-36), PDIA6 (p = 5.51E-33), PDIR (p = 1.81E-12), ERp57 (p = 9.13E-07), ERp72 (p = 3.65E-22), and AGR3 (p = 4.56E-24) expression in ovarian cancers compared to normal tissues." (PMID 29262583, 2017). "We sought to evaluate the expression of PDI, PDIA6, PDIR, ERp57, ERp72 and AGR3 in ovarian cancer patient samples and examine their prognostic significance." (PMID 29262583, 2017).
acute myocardial infarction (1 paper, 2019). Necrosis of the myocardium, as a result of interruption of the blood supply to the area. "However, the role of protein disulfide isomerase associated 6 (PDIA6) under hypoxic conditions in the myocardium remains enigmatic, and it is unknown whether the gut microbiota influences the expression of PDI and PDIA6 under conditions of acute myocardial infarction." (PMID 30498015, 2019). "The in vivo relevance of increased PDIA6 in cardiomyocytes, an established regulator of the UPR, was further demonstrated under conditions of AMI in the murine model of myocardial infarction (permanent LAD ligation)." (PMID 30498015, 2019). "In vivo, in the left anterior descending artery (LAD) ligation mouse model of acute myocardial infarction, similar to PDI, PDIA6 protein expression was enhanced in the infarcted area (LAD+) relative to uninfarcted sham tissue or the neighbouring area at risk (LAD–) of C57BL/6J mice." (PMID 30498015, 2019).
bipolar disorder (1 paper, 2016). A disorder of the brain that causes unusual shifts in mood, energy, activity levels and the ability to carry out day-to-day tasks. "Furthermore, we also found multiple SNPs that localize to PDIA3, PDIA6 and HYOU1 that link to either BMI or bipolar disorder." (PMID 27280443, 2016).
cardiac interstitial fibrosis (1 paper, 2021). "Interestingly, ER stress markers BiP and PDIA6 correlated with cardiac interstitial fibrosis in the animals, as well as CHOP correlating with collagen type I protein levels, thereby showing the possible role of ER stress in ECM production." (PMID 34439522, 2021).
clear cell ovarian carcinoma (1 paper, 2017). "Our results strongly suggest that PDI, PDIA6, PDIR, ERp57, ERp72 and AGR3 expression can be useful biomarkers for clear cell ovarian carcinoma but additional studies are required to further validate the prognostic role of PDIs in these cancers." (PMID 29262583, 2017). "In clear cell ovarian carcinoma PDI, PDIA6, PDIR, ERp72, ERp57 and AGR3 were overexpressed." (PMID 29262583, 2017). "However, PDI, PDIA6, PDIR, ERp72 and AGR3 are more significantly overexpressed (p<0.001) than ERp57 (p<0.05) in clear cell ovarian carcinoma." (PMID 29262583, 2017).
colon cancer (1 paper, 2022). "Consistent with previous reports, PDIA1 and PDIA3 were overexpressed in colon cancer tissues in comparison with that in their adjacent tissues, in addition to the overexpressed PDIA2; however, no statistic changes were detected for PDIA4, PDIA5, and PDIA6 expression." (PMID 35860571, 2022).
glioblastoma (1 paper, 2021). The most malignant astrocytic tumor (WHO grade IV). "However, glioblastoma U87MG cell migration and invasion were enhanced significantly after inhibition of PDIA6, suggesting that PDIA6 might play an inhibitory role in cell migration and invasion in glioblastoma." (PMID 33761940, 2021).
keloid (1 paper, 2022). An irregularly shaped, elevated mark on the skin caused by deposits of excessive amounts of collagen during wound healing. "In our research, we detected upregulated BiP and PDI, which help to correct the folding of proteins, including P4HB, PDIA3, and PDIA6 in keloids." (PMID 35435317, 2022).
lung squamous cell cancer (1 paper, 2023). "CAT, ENO1, NQO1, P4HB, and PDIA6 were unique to LUAD, while CAV1, GAPDH, GPX2, GPX3, and PDIA4 exhibited consistent trends in differential expression in both LUAD and lung squamous cell cancer, significant prognostic survival prediction (p<0.05), and excellent classification effectiveness." (PMID 37955007, 2023).
malnutrition (1 paper, 2020). Inadequate nutrition resulting from poor diet, malabsorption, or abnormal nutrient distribution. "The cluster formed CALR, HSPA5, P4HB and, PDIA6 is a potential indicator of maternal malnutrition on the endoplasmic reticulum dysfunction in the prostate of offspring since they act as the fundamental molecular machinery for correct protein folding and Ca2+ homeostasis." (PMID 33049715, 2020).
oral squamous cell carcinoma (1 paper, 2021). "Herein, we explored the role of protein disulfide isomerase family 6 (PDIA6) in the aerobic glycolysis and the progression of oral squamous cell carcinoma (OSCC)." (PMID 33761940, 2021).
Parkinson disease (1 paper, 2023). A progressive degenerative disorder of the central nervous system characterized by loss of dopamine producing neurons in the substantia nigra and the presence of Lewy bodies in the substantia nigra and locus coeruleus. "Some genes in these networks are important for neuronal function, such as NMDA receptor, and protein disulfide isomerase family A member 6 (Pdia6); high levels of PDIA6 in Parkinson’s Disease (PD) is associated with greater sensitivity to ER stress." (PMID 38201293, 2023).
renal cell carcinoma (1 paper, 2021). "Over-expression of FZD1 attenuated PDIA6 silencing-induced increase in cell apoptosis and decrease in cell proliferation in imatinib-resistant renal cell carcinoma cells." (PMID 34781823, 2021). "A498/R was transfected with shPDIA6 to investigate the effects of PDIA6 on imatinib-resistance of renal cell carcinoma." (PMID 34781823, 2021). "The down-regulated p-DNA-PK and Rad51 in A498/R with shPDIA6 transfection was up-regulated by the over-expression of FZD1, indicating that PDIA6 contributed to the imatinib-resistance of renal cell carcinoma through activation of Wnt3a-FZD1 pathway." (PMID 34781823, 2021). "Knockdown of PDIA6 down-regulated protein expression of p-DNA-PK and Rad51 in A498/R post incubation with imatinib, revealing that PDIA6 contributed to the DNA damage repair of imatinib-resistant renal cell carcinoma." (PMID 34781823, 2021). "Our results showed that knockdown of PDIA6 decreased Bcl-2 expression, increased Bax, and cleaved caspase-3 to reduce imatinib-resistance of renal cell carcinoma cells." (PMID 34781823, 2021). "Lastly, protein expression levels of Wnt3a and Frizzled1 (FZD1) in imatinib-resistant renal cell carcinoma cells were down-regulated by silencing of PDIA6." (PMID 34781823, 2021). "Protein expression levels of Wnt3a and FZD1 were down-regulated in A498/R, suggesting that PDIA6 contributed to the activation of Wnt3a-FZD1 pathway in imatinib-resistant renal cell carcinoma." (PMID 34781823, 2021). "In conclusion, knockdown of PDIA6 suppressed cell proliferation and DNA damage repair of imatinib-resistant renal cell carcinoma cell and promoted the cell apoptosis through down-regulation of Wnt3a and FZD1." (PMID 34781823, 2021). "Expression of PDIA6 in renal cell carcinoma was detected to investigate the role of PDIA6 in renal cell carcinoma." (PMID 34781823, 2021). "DNA damage repair biomarkers, p-DNA-PK and Rad51, were reduced by knockdown of PDIA6, suggesting that PDIA6 promoted DNA damage repair to enhance the resistance of renal cell carcinoma to imatinib." (PMID 34781823, 2021). "In conclusion, knockdown of PDIA6 sensitized imatinib-resistant renal cell carcinoma cells into imatinib through inactivation of Wnt3a-FZD1 axis." (PMID 34781823, 2021). "Data from qRT-PCR and western blot showed that PDIA6 was increased in renal cell carcinoma tissues compared with the normal tissues." (PMID 34781823, 2021). "First, PDIA6 was found to be up-regulated in the imatinib-resistant renal cell carcinoma tissues and cells." (PMID 34781823, 2021). "The effects of PDIA6 on proliferation, apoptosis, and DNA damage repair of imatinib-resistance of renal cell carcinoma were investigated." (PMID 34781823, 2021). "Secondly, cell proliferation of imatinib-resistant renal cell carcinoma cells was suppressed by PDIA6 silencing, and the apoptosis was promoted with reduced Bcl-2, enhanced Bax and cleaved caspase-3." (PMID 34781823, 2021). "Knockdown of PDIA6 suppressed cell proliferation and DNA damage repair and promoted the apoptosis of imatinib-resistance of renal cell carcinoma through inactivation of activation of Wnt3a-FZD1 signaling." (PMID 34781823, 2021). "Since PDIA6 was found to be an oncogene and contribute to the chemoresistance of cancer cells, the effect of PDIA6 on imatinib-resistant renal cell carcinoma was investigated in this study." (PMID 34781823, 2021). "The results showed that PDIA6 was up-regulated in imatinib-resistant renal cell carcinoma." (PMID 34781823, 2021). "Functional assays showed that knockdown of PDIA6 sensitized imatinib-resistant renal cell carcinoma cells to imatinib through decreasing the half-maximal inhibitory concentration (IC50) of imatinib-resistant renal cell carcinoma cells." (PMID 34781823, 2021). "PDIA6 was found to be up-regulated in imatinib-resistant renal cell carcinoma tissues and cells." (PMID 34781823, 2021).
renal cell carcinoma (continued). "In this study, the effect of PDIA6 on imatinib-resistance of renal cell carcinoma was investigated." (PMID 34781823, 2021). "In this study, we hypothesized that PDIA6 promoted the imatinib resistance of renal cell carcinoma." (PMID 34781823, 2021). "Moreover, the interference of PDIA6 increased phosphorylation of H2A histone family member X (γH2AX), while decreased Rad51 and phosphorylated DNA-dependent protein kinase (DNA-PK) (p-DNA-PK) in imatinib-resistant renal cell carcinoma cells." (PMID 34781823, 2021). "The role of PDIA6 in c-Jun and ERK pathways in imatinib-resistance of renal cell carcinoma should be investigated in further research." (PMID 34781823, 2021). "Silencing of PDIA6-induced decreases in p-DNA-PK and Rad51 was restored by over-expression of FZD1, suggesting that PDIA6 might contribute to the resistance of renal cell carcinoma to imatinib through activation of Wnt3a/FZD1 pathway." (PMID 34781823, 2021). "However, the effect of PDIA6 on progression of renal cell carcinoma has not been reported yet." (PMID 34781823, 2021).
serous ovarian cancer (1 paper, 2017). "PDI, PDIA6, PDIR, ERp57, ERp72 and AGR3 were highly expressed in serous ovarian cancer compared to normal tissues (p = <0.001)." (PMID 29262583, 2017).
squamous cell carcinoma (1 paper, 2013). A carcinoma arising from squamous epithelial cells. "PDIA6 serves as regulators of both cell metabolism and stress response, and overexpression of PDLA6 is involved in different cellular processes, including cell migration and cell division in squamous cell carcinomas." (PMID 23977302, 2013).
tuberculous meningitis (1 paper, 2012). "Those described previously included signal-regulatory protein alpha (SIRPA) and protein disulfide isomerase family A, member 6 (PDIA6), which have been shown to be overexpressed at the mRNA level in tuberculous meningitis." (PMID 23198679, 2012).
viral infection (1 paper, 2018). "Several studies also demonstrated the effects of down-regulation of PDIA3 and PDIA6 individually upon virus infection." (PMID 29404200, 2018). "Eight proteins (GPT2, HSPA9, MAPK1, PDIA3, PDIA6, PSMC5, TALDO1, and ATP5B) were predicted/known to be involved in viral infection." (PMID 29404200, 2018). "The change in abundance of eight of the targeted proteins (GPT2, HSPA9, MAPK1, PDIA3, PDIA6, PSMC5, TALDO1, and ATP5B) was predicted to collectively inhibit viral infection (pathway analysis)." (PMID 29404200, 2018). "Analysis using IPA software suggested that eight of the targeted proteins (ATP5B, GPT2, HSPA9, MAPK1, PDIA3, PDIA6, PSMC5, and TALDO1) were involved in virus infection and their lower protein abundance may inhibit viral infection." (PMID 29404200, 2018).
tumor (32 papers, 2013 to 2026). "The disulfide isomerase PDIA6 has been shown to enable shedding of tumor-associated NKG2D (natural killer group 2, member D) ligands that promote resistance to cancer, thus contributing to tumor immune escape." (PMID 31847321, 2019). "The tumor-associated proteins identified in study, PDIA6, MEG3, SDCCAG3, IGHG1 and IGHG3 have been previously reported to have cancer-associated properties." (PMID 23977302, 2013). "Upstream, tumor-stromal interactions may contribute to PDIA6 upregulation, as cancer-associated fibroblast-derived C-X-C motif chemokine ligand 12 (CXCL12) activated C-X-C chemokine receptor 4 (CXCR4)-dependent signal transducer and activator of transcription 3 (STAT3) signaling in vitro." (PMID 42234404, 2026). "In vivo, PDIA6 knockdown suppresses tumor growth and liver metastasis, and synergistic SCD1 inhibition (CAY10566) yields efficacy superior to monotherapies." (PMID 42234404, 2026). "The corresponding heat map further proved that HSP90B1 was positively correlated with the six genes (HSPA5, PDIA3, MANF, PDIA4, CALR, and PDIA6) in various tumours." (PMID 36291587, 2022). "Occurrence of an antigen-specific IFN-g immune response was associated with smaller tumor volume in antigen vaccinated mice, as compared to PBS control mice except in PDIA6 in TgMMTV-neu mice." (PMID 33976232, 2021). "The only antigen that did not have a significant correlation between the antigen-specific IFN-g T cells and tumor volume was PDIA6 with an R2 of 0.10 (p = 0.31)." (PMID 33976232, 2021). "Previous studies have shown that the major histocompatibility complex class I chain-related protein A (MICA) is shed from tumor cells via PDIA6 reducing the disulfide bond between them, facilitating the escape of tumor cells from immune responses." (PMID 32023222, 2020). "Shedding of soluble MICA depends on its interaction with the chaperon molecule protein disulfide isomerase family A member six (PDIA6—best known as ERp5) on the surface of tumor cells." (PMID 30597841, 2018). "Integrated single-cell and bulk transcriptomic analyses identify protein disulfide isomerase A6 (PDIA6) as a tumor epithelial-enriched gene associated with advanced tumor‐ node‐metastasis (TNM) stage and unfavorable survival." (PMID 42234404, 2026). "PDIA6 mediated the tumor-promoting effects of RBM47 on PC cells." (PMID 39741300, 2024). "Based on these findings, investigating the role of these interactions among P4HB, PDIA4 and PDIA6 in driving aggressive tumor phenotypes, such as proliferation, invasion and metastasis, could uncover potential targets for anti-metastatic therapies." (PMID 38029391, 2023). "In addition, down-regulation of PDIA6 significantly inhibited the proliferation and invasion of BC, and reduced BC tumor volume, weight and metastasis." (PMID 37601252, 2023). "Finally, we studied PDIA6 role in the in vivo tumor formation ability of SCC9 cells." (PMID 33761940, 2021). "Among them, higher levels of major vault protein (MVP), disulfide-isomerase A6 (PDIA6), and hnRNP A1 were detected in GBM tumor tissues than in normal tissues (Gene Expression Profiling Interactive Analysis database)." (PMID 40340965, 2025). "The result showed that, in comparison with the OE-NC group, the tumor weight and volume were increased when PDIA6 was upregulated in SCC9 cells, suggesting that PDIA6 enhanced cell tumorigenesis in OSCC." (PMID 33761940, 2021). "Among highly perturbed gene pairs across multiple tumor types, we noted CXXC1, HSPA5, GSK3A, SERP1, PDIA6, FKBP14, and SCH1, which showed multiple co‐expression changes." (PMID 34698427, 2021). "Expression of PDI, PDIA6, PDIR, ERp57, ERP72 and AGR3 is significantly correlated with patients’ tumor stages (stage I, stage II, stage III, stage IV, p = <0.001)." (PMID 29262583, 2017).
tumor (continued). "Resting tumour cDC1s included cluster 5 enriched in transcripts involved in the unfolded protein response (UPR) such as Creld2, Hspa5, and Pdia6, as well as the clusters 2, 3 and 6 that expressed transcripts such as Fos, Jun, and Dusp1 and cluster 0 that expressed H2afz, Lyz2, Sub1." (PMID 40745918, 2025). "Ishikawa cells with or without stable PDIA6 knockdown was subcutaneously injected into the armpit of female nude mice in two groups, and the tumor size was observed periodically for 4 weeks." (PMID 38097564, 2023). "Western blot analysis of the tumor samples showed that ipomoeassin F significantly decreased the levels of PDAI6 and PDIA4 proteins, demonstrating the blocking effect of ipomoeassin F on PDIA6 and PDIA4 in vivo." (PMID 37705743, 2023). "In the present study, we revealed for the first time that PDIA6 was overexpressed in OSCC tissues and served as an oncogene to promote OSCC growth, migration, invasion, and in vivo tumor formation and inhibit cell apoptosis through enhancing aerobic glycolysis in OSCC." (PMID 33761940, 2021). "Additionally, PDIA6 functions as an oncogene to promote OSCC growth, migration, invasion, and in vivo tumor formation and inhibit cell apoptosis through enhancing aerobic glycolysis." (PMID 33761940, 2021). "We also identified six proteins (CALR, HIST2H2AC, HSPA5, P4HB, and PDIA6) in the HPA database that showed increased immunostaining in PCa tumor tissue, while low or not detected in normal prostate tissue." (PMID 33049715, 2020). "In this study, we focused on six PDI family proteins: PDIA6, PDIR, ERp57, ERp72, AGR3 and PDI, because these proteins have been found to promote tumor cell proliferation or have unknown cellular functions." (PMID 29262583, 2017). "We further constructed gene modules in AT2 (LUAD) and basal (LUSC) cells, which revealed that many tumor-related genes in cells from stage-I patients, including PIGR, AZGP1, BTG2, EGR1, and LMO3 in AT2 cells from LUAD, and AQP3, SPHK1, PPT1, and PDIA6 were found in basal cells from LUSC." (PMID 35027529, 2022).